RBFOX2 (RNA binding fox-1 homolog 2)
Diseases named in the same sentence as RBFOX2 in open-access papers (continued):
Sharing a sentence is not in itself a finding about the gene and the disease.
tumor (continued). "We note that the RBFOX family of proteins includes RBFOX1, RBFOX2, and RBFOX3; however, RBFOX1 and RBFOX3 show the greatest extent of downregulation across different tumours (>60-fold), whereas RBFOX2 shows comparatively moderate downregulation (~3-fold)." (PMID 35987939, 2022). "Collectively, these observations strongly suggest that elevated NEK2 levels in TNBC cells support a pro-mesenchymal splicing program by controlling RBFOX2 expression, thus enhancing tumor aggressiveness and invasiveness." (PMID 34930366, 2021). "Immunohistochemistry (IHC) analysis revealed that RBFOX2 expression was mainly presented in tumor cells." (PMID 34180133, 2021). "Rbfox2 localizes to cytoplasmic granules under stress conditions;22 however, the tumor microenvironment differs markedly from that of normal tissues with regard to stress-inducing conditions." (PMID 31028247, 2019). "To investigate Rbfox2 localization in tumor tissues, we examined the subcellular localization of Rbfox2 by immunofluorescence microscopy of cells derived from colon tissue." (PMID 31028247, 2019). "Immunohistochemistry analysis confirmed that ESRP1 and RBFOX2 protein were expressed in all tumor tissue areas, in agreement with literature data, but with different intensity and distribution." (PMID 27911856, 2017). "The analysis confirmed the presence of both ESRP1 and RBFOX2 protein expression in all tumor cell compartments, especially the nucleus." (PMID 27911856, 2017). "RBFOX2 is involved in tumour cell proliferation, invasion, migration and drug resistance." (PMID 39243148, 2024). "Notably, our findings unveiled an inverse relationship between RBFOX2 expression and both the T stage and tumor size (p = 0.024 for both)." (PMID 38881877, 2024). "The role of RNA‐binding fox‐1 homologue 2 (RBFOX2) in tumour progression." (PMID 39243148, 2024). "Taken together, these findings suggested that RBFOX2 may exhibit either oncogenic or suppressive properties depending on the specific tumor type." (PMID 38881877, 2024). "In recent years, mounting evidence underscores the pivotal role of RBFOX2 in tumour progression." (PMID 39243148, 2024). "However, the promoter methylation was higher in tumor tissues, and a higher promoter methylation of RBFOX2 indicated worse OS for KIRP patients." (PMID 38881877, 2024). "Given that RBFOX2 nuclear depletion promotes aggressive in vitro phenotypes in PDAC cells, we next investigated whether RBFOX2 depletion impacted PDAC tumor development in vivo." (PMID 38114498, 2023). "Together, these in vivo data support a tumor suppressive role for RBFOX2 in metastatic progression." (PMID 38114498, 2023). "As EMT is generally linked to tumour progression and poor clinical outcome, several studies have indicated that EMT-linked alternative splicing patterns regulated by splicing regulators including RBFOX2 may be biomarkers of aggressive tumour types, especially in lung, breast, and colon cancer." (PMID 38002944, 2023). "Recent studies have demonstrated that RBFOX2 regulates the alternative splicing event of MPRIP, showing tumor suppressor potential for metastatic pancreatic cancer." (PMID 38881877, 2024). "RBFOX2 is involved in proliferation, epithelial–mesenchymal transition (EMT), differentiation and tumor development." (PMID 38881877, 2024). "To further validate our predictions, we overexpressed RBFOX2 in Luminal breast cells, chosen after analysis of the RBPs expression patterns across CCLE breast cell lines, confirming the same trend observed for tumour subtypes." (PMID 36707502, 2023). "In the case of PAAD, RBFOX2 expression did not exhibit any noteworthy differences between tumor tissues and their matched normal tissues." (PMID 38881877, 2024).
tumor (continued). "Because PRMT5‐mediated Rbfox2 methylation is required for Rbfox2 ubiquitination and stabilization by FBXO7, we next explored the potential synergistic effects of FBXO7 silencing plus PRMT5 inhibition on GSC self‐renewal and tumor growth." (PMID 37822160, 2023). "Moreover, we observed that 21 splicing factor genes showed significantly differential AS between SS and tumor-adjacent tissues, such as HNRNPA1, PTBP2, QKI, RBFOX2, and TRA2A." (PMID 36118864, 2022). "RBFOX2 expression did not vary substantially among tumor areas, but it was slightly higher in MET 1 and 2 (grade 3 and 3+, respectively) than in NED 1 and 2 samples (grade 3 and 3, respectively)." (PMID 27911856, 2017). "However, our analysis of TCGA, GTEx, and CPTAC databases demonstrated that RBFOX2 expression was higher in LIHC tumor tissues compared to normal tissues." (PMID 38881877, 2024). "Importantly, we observed decreased RBFOX2 abundance in PDX-derived cell lines from PDAC patients with liver metastases (metastatic lines marked with asterisks), suggesting RBFOX2 may have a tumor suppressive role in progression to metastatic PDAC." (PMID 38114498, 2023).
heart diseases (3 papers, 2016 to 2024). "Our work provides evidence that changes in Tpm1 AS may contribute to heart and muscle defects observed in RBFOX2 loss of function in human heart diseases and experimental animal models." (PMID 34302435, 2021).
Cardiovascular disease (2 papers, 2022 to 2024). "Dysregulated RNA‐binding fox‐1 homologue 2 (RBFOX2) in cardiovascular diseases." (PMID 39243148, 2024).
neurodevelopmental disorder (1 paper, 2016). A behavioral and cognitive disorder with onset during the developmental period that involves impaired or aberrant development of intellectual, motor, or social functions. "It remains to be clarified if RBFOX3 and RBFOX2 are involved in the establishment of cortical architecture and neurodevelopmental disorders including ASD." (PMID 27481563, 2016).
RBFOX2 also shares sentences with these, for which no sentence is quoted: infection (4 papers); cardiac hypertrophy (2); hypertrophic cardiomyopathy (2); lung carcinoma (2); adenocarcinoma (1); Alzheimer disease (1); asthma (1); atherosclerosis (1); Autoimmunity (1); bipolar disorder (1); breast tumors (1); cerebellar ataxias (1); cleft palate (1); Diamond-Blackfan anemia (1); embryonal tumors (1); escherichia coli infection (1); esophageal cancer (1); Fanconi anemia (1); head and neck carcinoma (1); heart (1); Hepatitis B (1); Hepatitis C (1); ischemic cardiomyopathy (1); Kabuki syndrome (1); neurodevelopmental disabilities (1); non-small cell lung carcinoma (1); ovarian tumours (1); pheochromocytoma (1); prostate tumors (1); psoriasis (1).
A further 9 diseases each share a sentence with RBFOX2 in 1 paper.